PPIF (peptidylprolyl isomerase F)
Description:
PPIase that catalyzes the cis-trans isomerization of proline imidic peptide bonds in oligopeptides and may therefore assist protein folding. Involved in regulation of the mitochondrial permeability transition pore (mPTP). It is proposed that its association with the mPTP is masking a binding site for inhibiting inorganic phosphate (Pi) and promotes the open probability of the mPTP leading to apoptosis or necrosis; the requirement of the PPIase activity for this function is debated. Involved in modulation of mitochondrial membrane F(1)F(0) ATP synthase activity and regulation of mitochondrial matrix adenine nucleotide levels (By similarity). Has anti-apoptotic activity independently of mPTP and in cooperation with BCL2 inhibits cytochrome c-dependent apoptosis.
Synonyms: CyP-D; CypD; CyP-M; CYP3; hCyP3
Tractability: Small molecule: a structure with a bound ligand is known. PROTAC: ubiquitination databases record sites on it; its protein half-life has been measured; a small molecule that binds it is known.
Target class: Isomerase; Enzyme
Gene: Protein-coding gene on chromosome 10 (79,347,466 to 79,355,337, forward strand). Ensembl gene ENSG00000108179.
Subcellular location: Mitochondrion matrix
Subcellular location (Human Protein Atlas): Mitochondria
Gene Ontology:
Molecular function: peptidyl-prolyl cis-trans isomerase activity; protein binding; cyclosporin A binding; enzyme inhibitor activity
Biological process: cellular response to hydrogen peroxide; mitochondrial outer membrane permeabilization involved in programmed cell death; negative regulation of apoptotic process; negative regulation of intrinsic apoptotic signaling pathway; negative regulation of release of cytochrome c from mitochondria; regulation of mitochondrial membrane permeability; regulation of mitochondrial membrane permeability involved in programmed necrotic cell death; cellular response to arsenic-containing substance; cellular response to calcium ion; negative regulation of oxidative phosphorylation; protein folding; response to ischemia; programmed cell death
Cellular component: mitochondrial permeability transition pore complex; mitochondrion; membrane; mitochondrial matrix
Genetic constraint (gnomAD): Loss-of-function variants: 23 observed, 18.64 expected, observed/expected ratio (o/e) 1.23, 90% interval 0.89 to 1.73. The upper end of that interval is the gene's LOEUF score, 1.73, which puts it in group 6 of 6, group 1 being the genes least tolerant of losing a copy. Missense variants: 287 observed, 250.16 expected, observed/expected ratio (o/e) 1.15, 90% interval 1.04 to 1.26. Synonymous variants: 113 observed, 99.82 expected, observed/expected ratio (o/e) 1.13, 90% interval 0.97 to 1.32.
Homologues: Orthologues: chimpanzee PPIF (99% identical), macaque PPIF (97% identical), guinea pig PPIF (90% identical), pig PPIF (90% identical), dog PPIF (89% identical), mouse Ppif (89% identical), rat Ppif (71% identical), rabbit PPIF (68% identical), tropical clawed frog ppif (67% identical), zebrafish ppifb (65% identical), Drosophila melanogaster CG7768 (59% identical). Paralogues in human: PPIA (60% identical), PPIE (57% identical), PPIAL4C (53% identical), PPIAL4A (53% identical), PPIAL4D (52% identical), PPIAL4E (52% identical), PPIAL4F (52% identical), PPIAL4G (52% identical), PPIB (52% identical), PPIAL4H (52% identical), PPID (50% identical), PPIC (47% identical), and 10 more.
Diseases named in the same sentence as PPIF in open-access papers:
PPIF is named in the same sentence as 45 diseases in open-access papers, as found by Europe PMC text mining. Sharing a sentence is not in itself a finding about the gene and the disease. The quoted sentences say what the papers report.
breast carcinoma (4 papers, 2012 to 2025). "This revealed numerous genes whose expression was altered by reducing YB-1, including several related to hypoxia (e.g., PPIF, SLC3A2 and SLC7A1) and found to be elevated in breast cancers with increased expression or amplification of YB-1." (PMID 34294889, 2022). "Two genes (EEF1A2 and PPIF) could similarly separate ER+, TAM-treated breast tumors by DMFS, and their protein levels were measured in an ER+ breast cancer cell line model with exogenous ERRγ." (PMID 25971350, 2015). "ERRγ signaling is associated with poor DMFS in ER+, TAM-treated breast cancer, and ESRRG, EEF1A2, and PPIF comprise a 3-gene signaling node that may contribute to TAM resistance in the context of an active ERK/MAPK pathway." (PMID 25971350, 2015).
endometrial cancer (4 papers, 2021 to 2024). Primary or metastatic malignant neoplasm involving the endometrium (mucous membrane that lines the endometrial cavity). "Meanwhile, we found that TICRR and PPIF positive staining were present at a higher level in tissues with endometrial cancer than in tissues of paracancer endometrium." (PMID 33495413, 2021). "We then evaluated the expression patterns of TICRR and PPIF in a panel of endometrial cancer cell lines." (PMID 33495413, 2021). "Overexpression of PPIF confers poor prognosis in endometrial cancer." (PMID 36189275, 2022). "Likewise, overexpression of FLOT2 was shown to result in epithelial-mesenchymal transition of tumor cells and, thereby, metastasis in hepatocellular carcinoma and overexpression of PPIF was reported to be a poor prognostic sign in endometrial cancer." (PMID 36506940, 2022). "Silencing of TICRR and PPIF led to enhance the expression of epithelial marker E-cadherin and decrease the mesenchymal marker N-cadherin and metastasis associated genes MMP9 as well as proliferation-related marker CCND1, suggesting their involvement in the progression of endometrial cancer." (PMID 33495413, 2021). "TICRR and PPIF may promise to be potential therapeutic targets for endometrial cancer." (PMID 33495413, 2021). "Through a series of in vitro experiments, we found that silencing TICRR or PPIF resulted in a significant suppression of cell proliferation and migration and elevated the effect of progesterone, suggesting their critical role in the progression of endometrial carcinoma." (PMID 33495413, 2021). "Additional co-expression analysis studies have shown that AKT1, TICRR, PPIF, ANO1, and PTGDS are possible regulators of endometrial cancer tumorigenesis." (PMID 39596419, 2024). "Additionally, PPIF was reported to be involved in mitochondrial permeability transition regulated necrosis and necroptosis, while the correlation between PPIF and mitochondrial ROS production in the development of endometrial carcinoma had not been researched." (PMID 33495413, 2021). "Besides, we searched DrugBank database to find drugs that targeted oncogenes, showing that cyclosporine and triglyme may be of great value to suppress tumor growth by inhibiting the expression of PPIF, which had not been verified in both experimental and clinical study of endometrial carcinoma." (PMID 33495413, 2021).
psoriasis (4 papers, 2023 to 2025). An autoimmune condition characterized by red, well-delineated plaques with silvery scales that are usually on the extensor surfaces and scalp. "NETosis, implicated in the pathogenesis of psoriasis and PsA, is suppressed by PPIF in ANCA-associated vasculitis." (PMID 40560578, 2025). "Here, we demonstrate that in psoriasis, HKGs such as STAT3, PPIF, and EIF5A are co‐opted by the IL‐17/IL‐6 signaling axis to drive keratinocyte activation." (PMID 40959079, 2025). "Then, 5 potential hub genes (SOD2, PGD, PPIF, GYS1, AHCY) of psoriasis were identified by protein–protein interaction (PPI) networks using Metascape database." (PMID 36890558, 2023). "Together, the 5 hub genes (SOD2, PGD, PPIF, GYS1 and AHCY) play pivotal roles in the development of psoriasis." (PMID 36890558, 2023). "We found that SOD2, PGD, PPIF, GYS1 and AHCY are five hub genes in PPI networks, indicating the potential role in the psoriasis initiation and progression." (PMID 36890558, 2023). "We identified 34 housekeeping genes associated with psoriasis and observed that the co-expression relationships between six genes (APOL2, DCUN1D3, UBE2F, HIGD1A, PPIF, and STAT3) and known psoriasis-related genes differed significantly between diseased and healthy individuals." (PMID 40959079, 2025). "Five potential hub genes of psoriasis were obtained, including SOD2, PGD, PPIF, GYS1 and AHCY." (PMID 36890558, 2023). "However, the potential role of PGD, PPIF, GYS1 and AHCY has not been explored in psoriasis." (PMID 36890558, 2023).
Alzheimer disease (3 papers, 2023 to 2025). A progressive, neurodegenerative disease characterized by loss of function and death of nerve cells in several areas of the brain leading to loss of cognitive function such as memory and language. "Our KEGG pathway analysis indicated that PPIF (Hyper/Up) physically interacts with SLC25A5 (STRING-db PPI) and is implicated in the cGMP-PKG signaling pathway and Alzheimer’s disease pathway." (PMID 40217422, 2025). "While both SPHK2 and PPIF are overexpressed and likely contribute to neuronal death in both human patients with Huntington’s disease or Alzheimer’s disease and rodent models of these diseases, knockout or inhibition of these genes protects against neurodegeneration." (PMID 40310674, 2025).
cardiac ischemia (2 papers, 2010 to 2022). "Inhibition or genetic ablation of PPIF was found to confer resistance against myocardial ischemia/reperfusion injury and development of heart failure." (PMID 35563680, 2022).
COVID-19 (2 papers, 2022). A disease caused by infection with severe acute respiratory syndrome coronavirus 2. "PPIF, whose expression increased in the blood of COVID-19 patients, is a cyclophilin that is an essential component of the mitochondrial permeability transition pore." (PMID 35991542, 2022).
osteoporosis (2 papers, 2025). A condition of reduced bone mass, with decreased cortical thickness and a decrease in the number and size of the trabeculae of cancellous bone (but normal chemical composition), resulting in increased fracture incidence. "The use of three of them (HDAC6, IL-8, PPIF) as a diagnostic tool for IBD, combined with osteoporosis, demonstrated high diagnostic efficacy (AUC 0.80)." (PMID 40422241, 2025). "For example, in both IBD and osteoporosis, there is an upregulation of common NET-related genes, namely HDAC6, IL-8, SRC, PPIF, PLCG2, PIK3CD, MAP2K1, and AKT1." (PMID 40422241, 2025).
renal fibrosis (2 papers, 2022 to 2024). A final common manifestation of a wide variety of chronic kidney diseases characterized by glomerulosclerosis and tubulointerstitial fibrosis. "Therefore, both eCyPA and PPIF are involved in the pathogenesis of renal fibrosis and serve as the new therapeutic targets for treatment of CKD and renal fibrosis." (PMID 35673572, 2022). "By contrast, studies with the SfA-derived pancyclophilin inhibitor GS-642362, which targets PPIA, PPIB, and PPIF, in the unilateral ureteric obstruction (UUO) mouse model showed inhibition of renal fibrosis by preventing tubular epithelial cell death and neutrophil infiltration." (PMID 38900587, 2024).
anaplastic astrocytoma (1 paper, 2021). "In detail, one patient collected tumor specimens in all stages of MT in the present cohort.PRKCQ,PPIF,NRP1,MEFV,GGT1,FAN1, andBTKmutations were found in both DA and anaplastic astrocytoma, whereas mutations ofTBC1D19,ESRRA,DIAPH2,COG6, andCBWD3occurred in HGA." (PMID 34430964, 2021).
asthma (1 paper, 2025). "Although these findings support a functional link between HK2 and PPIF in regulating epithelial apoptosis, the precise integration of this pathway with other known regulators of epithelial cell death and airway inflammation in asthma remains unclear." (PMID 40643524, 2025).
diabetes (1 paper, 2025). "This study also identified an association between hypomethylation of these CpG loci and several CVD risk factors, including smoking (AHRR and PPIF), BMI (PPIF), and the combination of BMI, diabetes, and triglyceride levels (CPTIA)." (PMID 40076974, 2025).
endothelial dysfunction (1 paper, 2025). In vascular diseases, endothelial dysfunction is a systemic pathological state of the endothelium (the inner lining of blood vessels) and can be broadly defined as an imbalance between vasodilating and vasoconstricting substances produced by (or acting on) the endothelium. "Furthermore, increased acetylation of CypD, encoded by PPIF, can exacerbate endothelial dysfunction and hypertension by inducing mitochondrial dysfunction, both of which are critical factors in the pathogenesis of AS." (PMID 40433124, 2025).
hypogonadism (1 paper, 2025). A disorder characterized by decreased function of the gonads. "In colocalization analyses, we find that several variants associated with testosterone levels and hypogonadism risk are located in or near genes related to liver function (UGT2B17, BRI3, PRMT6, PPIF)." (PMID 40316537, 2025).
muscular dystrophies (1 paper, 2022). "The opening of the pore has been implicated in the pathophysiology of multiple diseases, such as muscular dystrophies, ischemia-reperfusion injury, and various neurological diseases, while inhibition of PPIF has been suggested as a therapeutic strategy to delay it." (PMID 35991542, 2022).
myocardial infarction (1 paper, 2019). Gross necrosis of the myocardium, as a result of interruption of the blood supply to the area, as in coronary thrombosis. "Six hub genes, including BCL3, HCK, PPIF, S100A9, SERPINA1, and TBC1D9B that differentiated on admission after myocardial infarction the HF patients from the non-HF ones, can serve as early prognostic biomarkers of post-AMI patients." (PMID 31850068, 2019).
osteoarthritis (1 paper, 2022). A noninflammatory degenerative joint disease occurring chiefly in older persons, characterized by degeneration of the articular cartilage, hypertrophy of bone at the margins and changes in the synovial membrane. "We also found that in conditions leading to pathological calcification such as osteoarthritis and osteophyte formation and cardiac valve calcification and associated with upregulated BMP/Smad signaling, PPIF expression is decreased." (PMID 35635445, 2022).
pressure ulcer (1 paper, 2024). "This was corroborated in the reanalysis of a published data set derived from similar samples, where pressure ulcer samples displayed a decrease in PPIF gene expression." (PMID 38564292, 2024).
synovial sarcoma (1 paper, 2003). "Interestingly, a gene encoding receptor for the drug cyclosporin A (PPIF) was overexpressed in synovial sarcoma." (PMID 12592363, 2003).
venous ulcers (1 paper, 2024). "This experiment confirmed the upregulation of PPIF expression both in acute and venous ulcers as compared with healthy skin (2-fold change, P < 0.05)." (PMID 38564292, 2024).
tumor (10 papers, 2017 to 2025). "Although its role in cancer is still unclear, recent studies reported that PPIF up-regulation seems to play a role in the tumor progression, through the Paf1/MEK/ERK pathway." (PMID 28686225, 2017). "In particular, the up-regulation of GTPase HRAS is associated with carcinoma, while up-regulation of Cortactin and down-regulation of YKT6 and DFFA are related to tumor cell invasiveness and down-regulation of PPIF/CypD may lead to steatosis." (PMID 36016316, 2022). "However, with APX2009 or Devimistat treatment or combination of the two, the levels of PPIF are increased about 5–tenfold indicating that inhibition of TCA is likely increasing tumor cell death." (PMID 34376225, 2021). "Analyses of gene expression levels of the PPIF gene (for CypD) and C1QBP (for C1qBP) genes show parallel expression patterns in almost all tissues in normal and tumour states." (PMID 41401049, 2025).
cancer (7 papers, 2017 to 2025). A tumor composed of atypical neoplastic, often pleomorphic cells that invade other tissues. "Meanwhile, we knocked down the expression of TICRR and PPIF in the cancer cell lines by transfection of siTICRR and siPPIF respectively, siTICRR-1 and siPPIF-2 with high transfection efficiency were used for subsequent experiments." (PMID 33495413, 2021). "Interestingly, under hypoxia PPIF is significantly downregulated, presumably one of the many transcriptional changes that allow cancer cells to survive hypoxic stress." (PMID 34376225, 2021). "Genes TICRR and PPIF were significantly overexpressed in cancer cells than in normal endometrial epithelial cells (EEC) compared with other genes, suggesting they may play a pivotal role in oncogenesis and were selected for the following research." (PMID 33495413, 2021).
neurodegenerative disease (1 paper, 2022). A disorder of the central nervous system characterized by gradual and progressive loss of neural tissue and neurologic function. "In the “mitochondrial dysfunction in neurodegenerative disease” pathway, the DEG PPIF is linked to the ANT gene." (PMID 35804531, 2022).
PPIF also shares sentences with these, for which no sentence is quoted: infection (5 papers); Cirrhosis (2); fungal infection (2); heart failure (2); Huntington disease (2); ANCA-associated vasculitis (1); breast tumors (1); cholelithiasis (1); cognitive decline (1); dilated cardiomyopathy (1); hepatocellular carcinoma (1); inflammatory bowel disease (1); Insulin resistance (1); liver diseases (1); myopathies (1); nephrotic syndrome (1); neurological diseases (1); Obesity (1); ovarian carcinoma (1); sarcopenia (1); steatosis (1); ureteric obstruction (1); virus infection (1).